FGF7 (fibroblast growth factor 7)
Description:
Plays an important role in the regulation of embryonic development, cell proliferation and cell differentiation. Required for normal branching morphogenesis. Growth factor active on keratinocytes. Possible major paracrine effector of normal epithelial cell proliferation.
Synonyms: HBGF-7; KGF
Tractability: Antibody: its Gene Ontology location is reachable by antibodies, with high confidence; UniProt places it where antibodies can reach, with medium confidence; UniProt predicts a signal peptide or a membrane-spanning region.
Target class: Secreted protein
Gene: Protein-coding gene on chromosome 15 (49,423,170 to 49,488,775, forward strand). Ensembl gene ENSG00000140285.
Subcellular location: Secreted
Subcellular location (Human Protein Atlas): Nucleoli; Nucleoplasm; Predicted to be secreted
Pathways (Reactome):
Signal Transduction: FGFR2b ligand binding and activation; FRS-mediated FGFR2 signaling; Negative regulation of FGFR2 signaling; PI-3K cascade:FGFR2; PI3K Cascade; PI5P, PP2A and IER3 Regulate PI3K/AKT Signaling; PIP3 activates AKT signaling; Phospholipase C-mediated cascade; FGFR2; RAF/MAP kinase cascade; SHC-mediated cascade:FGFR2
Disease: Activated point mutants of FGFR2; Constitutive Signaling by Aberrant PI3K in Cancer; Signaling by FGFR2 in disease
Developmental Biology: Developmental Lineage of Multipotent Pancreatic Progenitor Cells
Gene Ontology:
Molecular function: chemoattractant activity; protein binding; growth factor activity; type 2 fibroblast growth factor receptor binding
Biological process: actin cytoskeleton organization; fibroblast growth factor receptor signaling pathway; mesenchymal cell proliferation; positive chemotaxis; positive regulation of cell population proliferation; positive regulation of epithelial cell proliferation; positive regulation of epithelial cell proliferation involved in lung morphogenesis; positive regulation of keratinocyte migration; positive regulation of keratinocyte proliferation; positive regulation of peptidyl-tyrosine phosphorylation; protein localization to cell surface; secretion by lung epithelial cell involved in lung growth; epidermis development; lung development; neurogenesis; positive regulation of MAPK cascade; regulation of cell migration; response to wounding; signal transduction; positive regulation of DNA-templated transcription; regulation of synapse maturation
Cellular component: cytoplasm; extracellular region; GABA-ergic synapse; Golgi apparatus; postsynapse
Genetic constraint (gnomAD): Loss-of-function variants: 3 observed, 12.06 expected, observed/expected ratio (o/e) 0.25, 90% interval 0.11 to 0.64. The upper end of that interval is the gene's LOEUF score, 0.64, which puts it in group 2 of 6, group 1 being the genes least tolerant of losing a copy. Missense variants: 103 observed, 142.06 expected, observed/expected ratio (o/e) 0.73, 90% interval 0.62 to 0.85. Synonymous variants: 49 observed, 48.92 expected, observed/expected ratio (o/e) 1, 90% interval 0.8 to 1.27.
Homologues: Orthologues: chimpanzee FGF7 (100% identical), macaque FGF7 (100% identical), rabbit FGF7 (97% identical), pig FGF7 (97% identical), mouse Fgf7 (94% identical), rat Fgf7 (93% identical), guinea pig FGF7 (91% identical), tropical clawed frog fgf7 (76% identical), zebrafish fgf7 (45% identical). Paralogues in human: FGF10 (45% identical), FGF22 (35% identical), FGF3 (35% identical), FGF20 (34% identical), FGF5 (34% identical), FGF16 (32% identical), FGF9 (32% identical), FGF6 (31% identical), FGF4 (29% identical), FGF11 (27% identical), FGF1 (26% identical), FGF14 (26% identical), and 9 more.
Diseases named in the same sentence as FGF7 in open-access papers:
FGF7 is named in the same sentence as 214 diseases in open-access papers, as found by Europe PMC text mining. Sharing a sentence is not in itself a finding about the gene and the disease. The quoted sentences say what the papers report.
breast carcinoma (32 papers, 1997 to 2026). "For example, FGF7, FGF10, and FGF22 bind exclusively to FGFR2 IIIb, with FGFR2 IIIb/FGF10 being highly associated with breast cancer development." (PMID 39596875, 2024). "The change in PR activity by FGF7/FGFR/JunB also changes the response of ER+ breast cancer cells to anti-ER therapies." (PMID 39596875, 2024). "Altogether, these data show that FGF7 signalling through FGFR2b is crucial for promoting breast cancer through different mechanisms and drives resistance to conventional therapies." (PMID 35193394, 2022). "FGF7 is detected in both stroma and tumour cells and increases breast cancer cell proliferation and migration in vitro." (PMID 35193394, 2022). "The breast cancer cell lines were treated with FGF7 or FGF10 for 1 or 8 min., and such early signalling was analysed using phosphoproteomics, hereafter referred to as trafficking phosphoproteomics approach 1 (TPA1)." (PMID 34086370, 2021). "Among the FGF7 subfamily, FGF3 and FGF7 have been reported to be highly expressed in breast cancer and gastric adenocarcinoma, respectively." (PMID 33935975, 2021). "Herein we showed for the first time that in MCF7, T47D and BT474 breast cancer cell lines, phosphorylation of PR at Ser294 and subsequent downregulation of PR protein level was induced by FGF7/FGFR2 (fibroblast growth receptor 2)-triggered signalling." (PMID 27852068, 2016). "FGF7 and FGF10 bind the epithelial b isoforms of FGFR1 and 2, with FGF7 being more specific for FGFR2b; they are potent mitogens that play crucial roles, among others, in wound healing, development, and cancer, including breast cancer." (PMID 41131959, 2026). "Notably, in certain epithelial cancers such as lung, bladder, and breast cancers, FGF7's overexpression has been observed." (PMID 38491511, 2024). "The activation of the FGF7/FGFR2 axis may cause the degradation of the ER and thus prevent tamoxifen from inhibiting ER+ breast cancer." (PMID 39596875, 2024). "Additionally, FGF7/FGFR2 signaling was found to abolish the anti-estrogenic effect of progesterone in breast cancer cells." (PMID 36009407, 2022). "Additionally, similar effects of FGF7 stimulation on AKT phosphorylation following PLAC1 knockdown in breast cancer cell lines SkBr3 and T47D were shown." (PMID 32499871, 2020). "It should be mentioned that, in breast cancer cells, the activation of the FGF7/FGFR2 axis may induce the proteasomal degradation of ER, preventing the inhibitory effects elicited by tamoxifen." (PMID 33081025, 2020). "Moreover, previous reports from other laboratories have confirmed that human breast cancer cells are generally in close contact with fibroblasts that express abundant FGF-7." (PMID 16176582, 2005). "In research on breast cancer, BBR treatment blocked breast cancer cell growth and metastasis partly by regulating METTL3-mediated m6A modification of FGF7 mRNA." (PMID 40829428, 2025). "The genes are associated with laryngeal cancer (MEOX2), cervical cancer (FGF7), oral cancer (DPT), breast cancer (CILP) or ovarian cancer (TMEM119) and LAMP3-positive dendritic cells are generally associated with cancer." (PMID 38671536, 2024). "By competitively binding miR-489-5p to elevate FGF7 expression and enhancing downstream AKT signaling, LINC00460 promotes breast cancer progression." (PMID 37251440, 2023). "Specifically in breast cancer, linc00460 was shown to serve as a ceRNA for Fibroblast Growth Factor 7 (FGF-7) mRNA by sponging miR-489-5p leading to upregulation of FGF7 expression and AKT activity and ultimately oncogenesis." (PMID 36139687, 2022). "Significantly overexpressed genes (CLDN7, MLLT10, RBM33, SH3RF1, SSBP4, and UBE2Z) were correlated with shorter survival, whereas underexpressed genes (BMPER, FGF7, MSRB3, and TNRC6B) were correlated with longer survival in breast cancer." (PMID 34151730, 2021).
breast carcinoma (continued). "The significant DEGs (CLDN7, BMPER, FGF7, MSRB3) in breast cancer samples compared to normal samples also showed coincident results of significant gene identification." (PMID 34151730, 2021). "The significantly underexpressed genes (BMPER, FGF7, MSRB3, and TNRC6B) in breast cancer were correlated with a longer survival time based on GSE42568 and GSE37751 (P> 0.05), this correlation cannot be demonstrated." (PMID 34151730, 2021). "Evaluation of cellular effects of the cross-talk between FGF7/FGFR2 and PR revealed that FGF7 or Pg, tested separately, stimulated anchorage-independent growth and migration of breast cancer cells." (PMID 27852068, 2016). "Results of our study showed that stimulation of PR(+) breast cancer cell lines with various FGFs decreased level of PR with the highest impact being observed for FGF1, FGF4, FGF7." (PMID 27852068, 2016). "BBR could also blocked breast cancer cell growth and metastasis partly by regulating METTL3-mediated m6A modification of FGF7 Mrna." (PMID 40829428, 2025). "FGF7 and FGF10 are among the components of breast cancer organoid growth medium, indicating that they both play a crucial role in the initiation and/or maintenance of breast cancer." (PMID 35193394, 2022). "In conclusion, FGF7 and FGF10 in the breast cancer microenvironment might regulate FGFR2 signalling-dependent breast cancer cell behaviour through complementary molecular mechanisms." (PMID 35193394, 2022). "We demonstrate firsthand the potential role of PLAC1 in the tumorigenesis of breast cancer cells and choriocarcinoma cells via formation of a trimeric complex between PLAC1, FGF7, and FGFR2IIIb, which binds to HSGAGs in the ECM, and leads to cell proliferation via the activation of AKT." (PMID 32499871, 2020). "FGF7, also secreted by breast fibroblasts, has similarly been suggested to act as a paracrine growth factor in human breast cancer, but our data do not demonstrate a significant link between FGF7 and FGFR2 expression." (PMID 21767389, 2011). "Neither heparin nor FGF-7, individually (18 ± 5 colonies, n = 3) or in combination (20 ± 7 colonies, n = 3) significantly changed the clonogenic growth of breast cancer cells cultured without fibroblasts." (PMID 16176582, 2005). "Neither heparin nor FGF-7, individually or in combination, produced any significant effect on the clonogenic growth of breast cancer cells cultured without fibroblasts." (PMID 16176582, 2005). "In this study, multiplex immunohistochemistry, drug testing of HR + /HER2- breast cancer organoids, single-cell sequencing, and primary cell coculture showed that the CDK4/6 inhibitor palbociclib promotes fibroblast senescence, thereby increasing IGF1 and FGF7 levels." (PMID 41986650, 2026). "Moreover, we show that heparin significantly interferes with the clonogenic growth of breast cancer cells co-cultured with fibroblasts in the presence or absence of exogenous FGF-7." (PMID 16176582, 2005). "Besides this, the release of FGF7 by CAFs and its interaction with the cognate receptor FGFR2 have been shown to induce ER phosphorylation, ubiquitination, and subsequent proteasomal degradation, therefore counteracting the endocrine treatment in breast cancer cells." (PMID 33081025, 2020). "In placental choriocarcinoma and breast cancer cells, we demonstrated that among members of the FGF family, PLAC1 exerts its function exclusively through FGF7, as we did not observe PLAC1 binding to other FGFs." (PMID 32499871, 2020).
oral mucositis (22 papers, 2008 to 2023). Inflammation of the mucous membranes of any of the structures in the mouth. "FGF7 expression is associated with healing and wound repair, supporting the integrity of the gastrointestinal tract mucosal barrier in chemotherapy patients who have oral mucositis." (PMID 26965559, 2016). "Keratinocyte growth factor-1 (KGF-1, also known as FGF-7) stimulates the growth of epithelial cells and protects those cells from chemotherapy or radiotherapy-induced oral mucositis." (PMID 28086221, 2017). "FGF7, in particular, is known to be cytoprotective for keratinocytes, with a recombinant form of FGF7 used clinically in the treatment of oral mucositis in patients undergoing bone marrow transplantation." (PMID 22737238, 2012). "Interestingly, a recombinant form of FGF7 is used clinically in the treatment of oral mucositis." (PMID 26798423, 2016). "Extrapolating the dose of FGF7 administered in a mouse via particles direct to the liver to humans on a weight for weight basis, the dose used in man via the HPV would be >250‐fold lower than the licensed dose for treating oral mucositis." (PMID 33428803, 2021).
mucositis (18 papers, 2012 to 2024). Mucositis is inflammation and damage of the mucous membranes lining the mouth and other parts of the gastrointestinal (GI) tract. "FGF7 has a potent ability to stimulate growth of intestinal epithelial and crypt cells and is used as an anti-mucositis conditioning agent to thicken the mucosal lining prior to cancer radiation therapy." (PMID 28207794, 2017). "Despite its short half-life (, Kepivance® package insert), studies have shown that FGF7 is a very effective conditioning agent prior to cancer radiotherapy to prevent mucositis." (PMID 28207794, 2017). "In addition, recombinant human FGF7 (and FGF20) has been used to treat mucositis in response to radiation therapy or as a medical countermeasure against radiation exposure." (PMID 33986387, 2021).
pulmonary fibrosis (16 papers, 2009 to 2026). Chronic progressive interstitial lung disorder characterized by the replacement of the lung tissue by connective tissue, leading to progressive dyspnea, respiratory failure, or right heart failure. "In the rodent bleomycin-model, enhanced Fgfr2b-signaling on alveolar epithelial cells via the exogenous application or induction of FGF10 or FGF7, conferred increased survival and reduced lung fibrosis." (PMID 26138239, 2015). "In another study on FGFR antagonists, inhibition of endogenous FGFR2b ligands (FGF7 and FGF10) does not alter bleomycin-induced pulmonary fibrosis, suggesting that these ligands are not essential for fibrosis." (PMID 34383782, 2021).
gastric cancer (14 papers, 1996 to 2025). A primary or metastatic malignant neoplasm involving the stomach. "Upregulation of FGF-7 has been reported to be associated with many human neoplastic tumors of epithelial origin including pancreatic, breast and gastric cancer, thus underlying the oncogenic role of FGF-7." (PMID 24212658, 2011). "FGFR2 expression was elevated in gastric cancer tissues, and treatment of gastric cancer cells with FGF7 stimulated cell migration and invasion through thrombospondin upregulation." (PMID 33801580, 2021). "FGF7 is produced by fibroblasts inside the stomach and promotes proliferation of scirrhous gastric cancer cells via FGFR2 receptors; the production of HGF and TGF-β promotes infiltration in a similar manner." (PMID 23545898, 2013). "Knocking down thrombospondin 1 inhibited FGF7-induced gastric cancer growth and metastasis." (PMID 39766329, 2024). "The secretion of FGF7 (a ligand of fibroblast growth factor receptor 2 [FGFR]2) by gastric fibroblasts is likely to contribute in a paracrine manner to the remarkable cell proliferation seen in scirrhous gastric cancer with FGFR2 overexpression." (PMID 31703077, 2019). "The FGF7/FGFR2 signaling cascade has been found to upregulate thrombospondin 1 (THBS1), promoting invasion and migration of gastric cancer cells." (PMID 38491511, 2024). "CAFs derived‐FGF7 is a mesenchyme‐specific heparin‐binding growth factor, which can bind to FGFR2 and promote cell migration and invasion in gastric cancer by upregulating THBS1 and elevating the activity of the PI3K/Akt/mTOR signaling pathway." (PMID 38778448, 2024). "Another explored axis that promotes EMT in gastric cancer involved the sequestering of miR-212-3p by linc-ROR to express the fibroblast growth factor 7 (FGF7), contributing to promoting migratory and invasive capabilities of gastric cancer cell lines." (PMID 36827545, 2023). "In gastric cancer, IRX1 acts a tumor suppressor through downregulation of BDKRB2, FGF7, and HIST2H2BE expression and inhibiting angiogenesis and cell proliferation." (PMID 33256112, 2020).
colitis (12 papers, 2012 to 2025). Inflammation of the colon. "FGF7 treatment following colitis induction led to therapeutic benefits such as diminished intestine ulceration and reduced cell death." (PMID 31921841, 2019). "Recombinant FGF7 treatment has also been tested in the context of DSS-induced colitis injury in rats and mice." (PMID 31921841, 2019). "Interestingly, in these models, FGF7 delivered before colitis induction was not protective against injury." (PMID 31921841, 2019).
diabetes (9 papers, 2009 to 2024). "The serum samples from COVID-19 patients exhibit the heterogeneous FGF7 concentrations in each individual, but FGF7 levels increase with the severity of COVID-19 in diabetes, implying a potential relationship between FGF7 and diabetes." (PMID 38654010, 2024). "The COVID-19 patients with preexisting diabetes and severe respiratory symptoms included more elderly patients and had higher serum FGF7 concentration." (PMID 38654010, 2024). "Most importantly, we show, for the first time, that FGF7 mRNA expression is significantly decreased during wound healing under diabetes conditions, contrary to what is observed in wound healing in healthy mice." (PMID 30967591, 2019). "The determined cutoff value based on the sensitivity and specificity for distinguishing mild and severe cases was 13.7 ng/ml, which could be considered as a serum FGF7 indicator for distinguishing severe from mild COVID-19 comorbid with diabetes." (PMID 38654010, 2024). "Receiver operating characteristic (ROC) curve analysis of the serum FGF7 concentration indicated an area under the curve (AUC) of 0.68 ± 0.05 for COVID-19 patients without diabetes, suggesting lower diagnostic accuracy." (PMID 38654010, 2024). "Our clinical retrospective study found the higher serum FGF7 could serve as a promising biomarker for assessing COVID-19 severity in diabetes." (PMID 38654010, 2024). "Taken together, our research offers a potential regulatory strategy for ACE2 by controlling FGF7, thereby protecting islets from SARS-CoV-2 infection and preventing the progression of diabetes in the context of COVID-19." (PMID 38654010, 2024). "Therefore, hMSC-EC secretome, particularly a cocktail of angiopoietin-1 and 2, FGF-7, MMP-9, and VEGF-C, are potential new therapeutic targets for improving wound-healing in diabetes." (PMID 35055129, 2022). "More importantly, key genes of the respective pathways, such as AKT3, FGF2, FGF7, mitogen-activated protein kinase 4 (MAP3K4), MAP3K5, insulin receptor (INSR), AKT3, and mTOR, were also enriched in the analysis, thus explaining the link between diabetes and BCRL subjects in the present study." (PMID 36232660, 2022). "Mice receiving islets and FGF7‐GAL‐PLGA particles had tighter glycemic control versus those receiving islets alone with blood glucose levels normalizing by day 30 posttransplant (p = .03) and with a greater proportion achieving a cure from their diabetes (75% vs. 0%; p < .001)." (PMID 33428803, 2021). "Moreover, miR-155 also targets fibroblast growth factor (FGF7) (also known as Keratinocyte growth factor, KGF), and by decreasing FGF7, diabetes-induced miR-155 impairs re-epithelization, while miR-155 inhibition mediates de-repression of FGF7 and accelerates wound closure." (PMID 33023156, 2020).
injury (8 papers, 2013 to 2022). Damage inflicted on the body as the direct or indirect result of an external force, with or without disruption of structural continuity. "During lung development, FGF7 and FGF10 stimulate epithelial cell proliferation and distal alveolar development, respectively, and are able to promote lung repair of the adult lung after acute lung injury." (PMID 35675358, 2022). "In a murine model of LPS-induced acute lung injury, experimental data suggested that human MSC-EV-transferred fibroblast growth factor 7 (FGF7, also known as keratinocyte growth factor) mRNA could mediate the therapeutic effects of MSCs." (PMID 31781552, 2019).